SNORD14 (Small nucleolar RNA SNORD14 )
Gene: Small nucleolar RNA gene on chromosome 2 (24,969,388 to 24,969,477, reverse strand). Ensembl gene ENSG00000202479.
Homologues: Orthologues: chimpanzee SNORD14 (100% identical), pig SNORD14 (89% identical), rabbit SNORD14 (87% identical), mouse Snord14a (80% identical), rat Snord14a (80% identical), tropical clawed frog SNORD14 (73% identical), guinea pig SNORD14 (61% identical). Paralogues in human: SNORD14B (91% identical), SNORD14A (74% identical), SNORD14C (67% identical), SNORD14E (67% identical), SNORD14D (59% identical).
Diseases named in the same sentence as SNORD14 in open-access papers:
SNORD14 is named in the same sentence as 3 diseases in open-access papers, as found by Europe PMC text mining. Sharing a sentence is not in itself a finding about the gene and the disease. The quoted sentences say what the papers report.
breast carcinoma (1 paper, 2020). "This SNP is also highly significantly associated with expression of NCR3LG1, KCNJ11, and SNORD14 genes with fragmentary and elusive data on association with breast cancer." (PMID 33334016, 2020).
SNORD14 also shares sentences with these, for which no sentence is quoted: diabetes (1 paper); Obesity (1).